MYC (MYC proto-oncogene, bHLH transcription factor)
Diseases named in the same sentence as MYC in open-access papers (continued):
Sharing a sentence is not in itself a finding about the gene and the disease.
medulloblastoma (continued). "Similarly, MYC-overexpressing medulloblastoma cells treated with AZD1152 were more sensitive to apoptosis than the low-expressing parent cell line, as was true for medulloblastoma cells with endogenous MYC overexpression." (PMID 33322239, 2020). "The MYC-driven induction of the promoter activity and the expression levels of miR-193a suggests that MYC could induce miR-193a expression in the WNT subgroup medulloblastomas." (PMID 32410663, 2020). "Group 3 medulloblastomas with amplified MYC have a negative prognosis." (PMID 30279357, 2018). "Ectopic expression of c-MYC could also, in collaboration with RE1-silencing transcription factor/neuron-restrictive silencer factor (REST/NRSF), block the neuronal differentiation of granule progenitor cells and drive medulloblastoma in mice." (PMID 28333115, 2017). "Analysis of H&E spinal cord sections revealed micrometastasis in 3/4 vehicle treated mice and 4/5 AZD1152-HQPA treated mice on day 7 of treatment, suggesting that Aurora B inhibition does not alter the propensity for metastasis in MYC amplified medulloblastoma cells." (PMID 25739120, 2015). "In addition to the BRCA2 6174delT, the medulloblastoma cells had amplification of MYC, deletion at Xp11.2, and isochromosome 17, but no structural variations or overexpression of GFI1 or GFI1B." (PMID 26380221, 2015). "However, MYC amplification, most frequent in Group 3 medulloblastomas, is not prognostic within this subgroup." (PMID 22358457, 2012). "Additionally, their medulloblastoma model showed sensitivity towards tazemetostat, an EZH2 inhibitor, suggesting it may be a potential drug for Group 3 medulloblastoma patients overexpressing OTX2 and c-MYC." (PMID 36831595, 2023). "MEB-Med-8A, D283 Med and D341 Med exhibit distinct characteristics such as MYC-amplification and occurrence of isochromosome 17 of the most aggressive group of tumors within the Non-WNT/Non-SHH group of medulloblastoma." (PMID 28159923, 2017). "In fact, we demonstrate that ALP down-regulates several cell cycle related genes, including MYC, and, unlike PL, treatment with ALP reverses the gene expression profile of Group 3 medulloblastoma cell lines." (PMID 26061748, 2015). "Expression of BRD4 is not increased in medulloblastoma samples compared to normal cerebellum further suggesting the activity of JQ1 is due to BRD4 mediated, c-MYC driven signaling." (PMID 24796395, 2014). "Likewise, different SCLCs have amplified MYC, MYCN, or MYCL, and different medulloblastoma subgroups overexpress either MYC or MYCN but not both." (PMID 33425720, 2020). "However, there was minimal effect of EPZ015666 on growth inhibition of non-MYC amplified medulloblastoma cells even at higher doses, suggesting anti-neoplastic specificity of EPZ015666 to MYC-dependent tumors." (PMID 31694585, 2019). "Although results showed some degree of correlation (R-value = 0.069–0.284; p-value = 0.111–0.606) of these genes in the other three medulloblastoma subgroups, none of these medulloblastoma subgroups showed a significant correlation between PRMT5 and MYC expression." (PMID 31694585, 2019). "MYC and MYCN amplification have been described as important negative prognostic factors in pediatric medulloblastoma, and the negative impact of MYC amplification could be confirmed in adults." (PMID 27781424, 2016).
glioblastoma (275 papers, 2009 to 2026). The most malignant astrocytic tumor (WHO grade IV). "The dysregulation of MYC has been associated with brain damage, including malignant primary brain tumors such as glioblastoma, which pose significant treatment challenges and carry poor prognoses." (PMID 39129166, 2025). "Recently, the association of PRMT5 with MYC was found in numerous cancers, including brain tumors such as glioblastoma; this association creates abnormalities in MYC function." (PMID 38136401, 2023). "Fourth, BMRF.P identified the relationship between MYC and MCL1, where the transcription factor c-Myc of MYC was associated with the regulation the proliferation and survival of glioblastoma stem cells." (PMID 36437931, 2022). "The light-activated drug, Verteporfin, inhibits the growth of glioblastoma cells by downregulating YAP-TEAD-associated downstream signaling molecules such as c-MYC, CTGF, and CYR6157." (PMID 31541175, 2019). "Recently, protein arginine methyl transferase (PRMT) 5 expression has been closely associated with aberrant MYC function in various cancers, including brain tumors such as glioblastoma." (PMID 31694585, 2019). "Increased BET activities have been associated with NUT midline carcinoma (NMC), glioblastoma and various haematological malignancies, through aberrant transcription of disease-associated genes and oncogenes such as MYC." (PMID 28148257, 2017). "To explore the possible role of c-MYC in tuning gene expression changes in hypoxia, we transduced the glioblastoma cell line U87MG with a lentiviral vector encoding a doxycycline (DOX)-inducible, Flag-tagged Omomyc construct." (PMID 27119353, 2016). "MYC has been previously upregulated in cases of radiation-induced angiosarcoma and glioblastoma, with its expression associated with longer overall survival but here we see a strong and consistent downregulation in all endometrial cancer patients after radiotherapy." (PMID 28443095, 2017). "It transcriptionally increases PD-L1 gene expression via upregulating c-MYC, contributing to immune evasion in glioblastoma." (PMID 41540013, 2026). "For instance, neddylation augments the activity of Cullin1-F-box and WD repeat domain-containing 7 E3 ligase, which destabilizes c-MYC protein, decreasing PD-L1 expression and improving T cell killing in glioblastoma." (PMID 41540013, 2026). "In glioblastoma there is little data about the effects of the p63 protein, but the increased expression of TA-p63 inhibits the expression of a well-known oncogene, MYC, reducing the cell proliferation and invasiveness." (PMID 40498028, 2025). "USP28 is similarly overexpressed in glioblastoma, contributing to tumorigenicity through MYC regulation." (PMID 40370434, 2025). "eccDNAs carrying multiple copies of EGFR in glioblastoma and MYC in small-cell lung cancer have been shown to promote excessive proliferation and resistance to targeted therapies." (PMID 41311372, 2025). "Intriguingly, upon EGF receptor activation, PKM2 binds histone H3 and phosphorylates histone H3 at T11, resulting in the acetylation of histone H3 at K9 to activate CCND1 and MYC expression in glioblastoma cells." (PMID 40059196, 2025).
glioblastoma (continued). "These compounds exhibit efficacy across a spectrum of solid tumors and hematological neoplasms, offering hope for patients with MYC-driven cancers, metastatic neuroblastoma, glioblastoma multiforme, and various others." (PMID 38975181, 2024). "In glioblastoma cells, the sensitivity to glutamine deprivation depends on c-MYC and can be inhibited by targeting MYC expression." (PMID 38459595, 2024). "For example, in glioblastoma stem cells, m6A-modified MYC is recognized by YTHDF2, while in acute myeloid leukemia, it is recognized by IGF2BP2." (PMID 38879589, 2024). "For example, TRIP13 is highly expressed in Glioblastoma and its inhibition impaired the proliferation, migration, and invasion of tumor cells by regulating c-MYC stability." (PMID 38464090, 2024). "Using another cancer type as an example, MED30 knockdown reduces tumor growth particularly in MYC high-expressed glioblastoma (GBM) cell lines." (PMID 38766212, 2024). "In summary, our findings highlight the role of MAD2L2 in influencing glioblastoma stem cells maintenance through the regulation of c-MYC, thereby impacting malignant behaviors." (PMID 38017538, 2023). "Our study elucidated the role of MAD2L2 in maintaining glioblastoma stemness and promoting malignant behaviors through the regulation of c-MYC, suggesting its potential as a therapeutic target." (PMID 38017538, 2023). "Further investigation revealed that MYC proto-oncogene (c-MYC) mediated the functional role of MAD2L2 in glioblastoma, which was further validated through a rescue experiment." (PMID 38017538, 2023). "Metabolic shift or enhanced glutamine metabolism is believed to occur in response to oncogenes such as c-MYC and pro-inflammatory cytokines in glioblastoma However, the exact mechanism by which this occurs is not fully understood in glioblastoma." (PMID 36834778, 2023). "PRMT1 can methylate MYC in myeloid and glioblastoma cells and modulate its transcriptional activity." (PMID 37310381, 2023). "The MYC gene, a proto-oncogene, is over-expressed in cerebral organoids; it is exhibited in brain tumors such as glioblastoma (GBM), central nervous system primitive neuroectodermal tumor, atypical teratoid/rhabdoid tumor, and medulloblastoma." (PMID 37222855, 2023). "A notable exception is in glioblastoma stem cells (GSCs), where GSCs with amplified MYC maintained oscillation and actually relied on CLOCK and BMAL1 to maintain stemness." (PMID 37639465, 2023). "The other three RNA oligos, FoxM1-p1 (13-nt, RRACH at 3’-end), c-Myc-p5 (8-nt), and c-Myc-p6 (11-nt, RRACH at 5’-end), were derived from the FOXM1 and MYC genes because of their involvement in m6A-mediated processes in glioblastoma and acute myeloid leukemia." (PMID 35060905, 2022). "FTO upregulated the MYC level, known as proto-oncogene TF, and downregulated the expression of MAX interactor 1 (MXI1), which binds to the MYC promoter and inhibits its expression, playing an oncosuppressor role in glioblastoma." (PMID 36012529, 2022). "The upregulation of MYC increases cell proliferation, migration, invasion, and clonogenicity of glioblastoma cells." (PMID 35740522, 2022). "Studies have demonstrated that c-MYC downregulation was capable of abolishing tumorigenicity exhibited by EZH2-depleted glioblastoma CSCs." (PMID 34745848, 2021). "In line with these experimental tumor models, patient-derived cancer stem cells (CSCs) of glioblastoma or acute myeloid leukemia display robust circadian rhythms despite high MYC expression levels." (PMID 33579708, 2021). "Preclinically, for glioblastomas, zotiraciclib has been shown in one study to potently suppress the growth of MYC-overexpressing glioblastoma cells, and higher MYC expression was correlated with greater sensitivity to the drug." (PMID 34207158, 2021).
glioblastoma (continued). "To extent these findings related to MYC phosphorylation/degradation further in the context of glioblastoma cells, we have generated a kinase-dead mutant of Aurora kinase A (D274N)." (PMID 34471141, 2021). "The role of c-MYC in ALK inhibitor resistance has been identified in some tumor types (glioblastoma, neuroblastoma, etc.)." (PMID 34063424, 2021). "Different from our findings and other studies, a recent study reported that YTHDF2 maintains the viability of glioblastoma stem cells by stabilizing MYC mRNA." (PMID 34544449, 2021). "The role of MYC as a sensitizer to PARPi-based therapy is also reported in patient-derived glioblastoma stem-like cells (GSCs), which show MYC or MYCN amplification and are more sensitized to PARPi when ATR activity is pharmacologically inhibited." (PMID 34201047, 2021). "Further underscoring diverse histone chaperone roles in maintenance of EBV latency, FACT was found to regulate EBV latency through effects on MYC expression, consistent with its role in driving glioblastoma oncogenic N-MYC expression." (PMID 33109754, 2020). "Mammalian IGF2BP proteins also appear to play a conserved role in stabilising MYC transcripts and are overexpressed in glioblastoma." (PMID 33092025, 2020). "Previously, MYC amplification has been discovered to promote homologous recombination via targeting CDK18 in glioblastoma." (PMID 33448691, 2020). "SOX2 mRNA was reported to contain m6A modification in embryonic stem cells and glioblastoma stem cells, and m6A modification of MYC mRNA was found in the CSCs of acute myeloid leukemia." (PMID 32676121, 2020). "MYC has been shown to drive an abnormal metabolic program in glioblastoma cells and inhibition of this pathway shows therapeutic benefit in animal models." (PMID 32631383, 2020). "The expression of OCT4, MYC, and KLF4 increases with increasing malignancy in astrocytomas, whereas MYC expression slightly decreases in recurrent glioblastomas." (PMID 31653034, 2019). "Here, the authors show that MYC amplified glioblastomas are sensitive to PARP inhibition due to CDK18 repression, which impairs ATR regulated homologous recombination repair, and that ATR inhibition sensitises glioblastomas to PARP inhibition." (PMID 31266951, 2019). "The combination treatment of PP242, a rapamycin kinase inhibitor and IRES-J007, MYC-IRES translation inhibitor significantly reduces tumor growth in glioblastoma (GBM) xenografts in mice." (PMID 28362357, 2017). "Here we demonstrate that inhibition of c-MYC in glioblastoma multiforme cells blunts hypoxia-dependent glycolytic reprogramming and mitochondria fragmentation in hypoxia." (PMID 27119353, 2016). "As compared to a nearly undetectable level in normal brain tissues, MYC is expressed in 80.6% of primary glioblastoma samples, and in 73% of astrocytomas." (PMID 27409345, 2016). "All these data suggest that c-MYC inhibition drives important metabolic changes in glioblastoma, so that the cells better preserve functional mitochondria in hypoxia and have a more pronounced oxidative phosphorylation phenotype and a reduced glycolytic one." (PMID 27119353, 2016). "For example, datasets for glioblastoma and breast invasive carcinoma reveal a significant correlation between MYC and POLRMT, with p values of < 0.001 and .002, respectively." (PMID 27590350, 2016). "Results indicated that MYC expression is significantly elevated in all glioblastoma subtypes relative to normal human cerebrum." (PMID 27409345, 2016). "This offers a plausible molecular mechanism that might contribute to the observed anti-proliferative effects of EGCG in c-MYC-driven cancers, such as glioblastoma." (PMID 40430538, 2025).
glioblastoma (continued). "In addition, B2M signaling in glioblastoma cells activates the PI3K/AKT/MYC/TGFβ1 axis, which sustains cancer stem cell properties and promotes M2-like macrophage polarization." (PMID 40842996, 2025). "Cell-based assays, such as c-MYC promoter-driven reporter gene assays (e.g., luciferase assays) in relevant cancer cell lines (like glioblastoma cells known to overexpress c-MYC), would be essential to determine if EGCG treatment leads to repression of c-MYC transcription." (PMID 40430538, 2025). "Consequently, the overexpression or deregulation of c-MYC is a frequent observation across a broad spectrum of human malignancies, including particularly challenging high-grade brain tumours like glioblastoma, where it correlates with poor prognosis." (PMID 40430538, 2025). "Glioblastoma cells treated with a combination of EPZ015666 and PP242 resulted in a significant loss of cell viability, an increase in the number of apoptotic cells and a reduction in the expression of c-MYC and cyclin D1." (PMID 39703687, 2024). "YY1 transcriptionally upregulates sentrin/SUMO-specific protease 1 (SENP1) and enhances the methylase activity of methyltransferase-like 3 (METTL3), leading to increased N6-Methyladenosine (m6A)-modification levels in MYC mRNA, which promotes the self-renewal of glioblastoma stem cells (GSCs)." (PMID 37444616, 2023). "As c-MYC has been shown to promote glutaminolysis in glioblastoma cells, we explored whether IL-11Rα expression correlated with c-MYC expression." (PMID 36834778, 2023). "MYC is a pro-tumorigenic gene upregulated in many types of cancers, including glioblastoma." (PMID 36834778, 2023). "YTHDF2 can stabilize MYC mRNA of cancer stem cells and it might be a potential target to regulate MYC signaling pathway in glioblastoma." (PMID 37598390, 2023). "This suggests that IL-11Rα may be inducing c-MYC expression which then may allow for glutaminolysis and enhanced survival of glioblastoma cells in glucose-depleted conditions." (PMID 36834778, 2023). "While in glioblastoma multiforme, MYC could directly increase miR-26a expression to regulate the tumor suppressor phosphatase and tensin homolog (PTEN)." (PMID 35120580, 2022). "In addition to interacting with MYC in glioblastoma, G9a positively regulates MYC transcription in a methyltransferase-independent manner by occupying the −2267 to −1949 region on the MYC promoter." (PMID 35740522, 2022). "In glioblastoma, YTHDF2 tended to be a therapeutic target; it could stabilize the transcripts of MYC and therefore regulate glucose metabolism in glioblastoma stem cells (GSCs)." (PMID 36686788, 2022). "MYC is of particular interest as a target in glioblastoma, given that it regulates about 15% of the entire genome, modulating cell proliferation, differentiation, survival, and apoptosis, and dysregulation in MYC signaling contributes to tumorigenesis." (PMID 34207158, 2021). "The latest WHO classification for CNS tumors which will be released in spring 2021 still recognizes glioblastomas with primitive neuronal component, and loss of GFAP expression, MYC/MYCN gene amplification, elevated Ki67 proliferation index and increased cerebrospinal fluid dissemination." (PMID 33876327, 2021). "In vitro, high expression of c-MYC and activation of the ERK1/2 pathway were associated with resistance against alectinib in ALK-expressing glioblastoma cells, and administration of a c-MYC inhibitor or MEK inhibitor was able to overcome TKI resistance and led to resensitization of resistant cells." (PMID 34063424, 2021). "Similarly, MYC is highly expressed in glioblastoma that can induce autophagy to inhibit apoptosis of hypoxic GBM cells." (PMID 33777735, 2021). "Moreover, our lab recently discovered that the transcription factor aryl hydrocarbon receptor (AHR), which is necessary for glioblastoma growth, mediates the expression of DHODH and UMPS in MYC-overexpressing fibroblasts and glioblastoma cells." (PMID 33201894, 2020).